FASN (fatty acid synthase)
Diseases named in the same sentence as FASN in open-access papers (continued):
Sharing a sentence is not in itself a finding about the gene and the disease.
tumor (continued). "To evaluate the impact of FASN-driven de novo FA synthesis on tumor cell responses to T cells, we performed impedance-based real-time monitoring of the cytolytic response to cell-based immunotherapy in co-isogenic cell lines that were either wild-type or deficient in the FASN gene." (PMID 39349429, 2024). "Moreover, host–tumor interaction could also be a possible explanation, considering that a previous study reported that fatty acid synthase pathway activation in primary tumor is associated with BMI and survival in patients with metastatic renal cell carcinoma." (PMID 34944964, 2021). "Furthermore, PI3K/Akt signaling has been linked to FASN expression in many tumor types." (PMID 29872506, 2018). "This complex enhances the EIF3F-mediated deubiquitination of FASN, increasing FASN stability and lipid synthesis, and accelerating tumor progression." (PMID 42231807, 2026). "Promising results have been shown by inhibitors like TVB-2640, which target FASN by disrupting fatty acid elongation to reduce membrane lipid synthesis and impair tumor growth." (PMID 41328353, 2026). "Either orlistat-mediated FASN inhibition or Y043-8015-induced disruption of the CCT2-EIF3F interaction effectively suppressed CCT2-driven tumor progression in vivo." (PMID 42231807, 2026). "Mechanistically, abundant cytokines (TNF-α, FGF) in the IE tumor microenvironment promote FASN and PARP9 expression." (PMID 41969226, 2026). "At the lipid metabolic level, fatty acid synthase (FASN)-mediated dysregulated fatty acid metabolism in CRC promotes tumor proliferation, metastasis, and immune microenvironment disorder." (PMID 41602397, 2026). "This enhances FASN protein stability, promotes lipid synthesis, and ultimately drives tumor progression." (PMID 41956989, 2026). "In GC, upregulation of enzymes such as fatty acid synthase (FASN) and transcription factors like SREBP1 has been reported, and both are emerging as tissue-based biomarkers associated with tumor progression and poor prognosis." (PMID 41244835, 2025). "It is known that tumor progression requires substantial energy and structural lipids, and FASN can promote lipid accumulation." (PMID 41427247, 2025). "For instance, inhibitors of fatty acid synthase (FASN) have demonstrated efficacy in preclinical models by disrupting lipid biosynthesis essential for tumor cell membranes and signaling molecules." (PMID 40214448, 2025). "Combined treatment with miR-532-5p and the FASN inhibitor orlistat can further suppress tumor growth and LNM." (PMID 40002387, 2025). "To investigate the effects of bufalin on fatty acid synthesis in vivo, we used an ELISA kit to measure FASN content in tumor tissues." (PMID 40942159, 2025). "In UC, FASN is differentially expressed in normal vs. tumor tissue, can independently predict muscle invasion, and is associated with cisplatin resistance." (PMID 40643470, 2025). "Subsequently, real-time PCR was conducted to measure FASN expression in the tumor spheroids, revealing a significant upregulation of FASN in the spheroid cells." (PMID 40901481, 2025). "We discovered that high expression of PUMA stabilizes FASN through USP15, forming a PUMA–USP15–FASN axis that promotes tumor progression and lipid accumulation." (PMID 40533456, 2025). "The overexpression of key enzymes such as Acyl-CoA Synthetase Long Chain Family Member 4 (ACSL4), FASN, and HMG-CoA in TNBC cells is strongly associated with tumor proliferation and metastasis." (PMID 40510158, 2025). "As a sponge of miR-330-5p and miR-326, circFARSA alleviated the inhibition of FASN and promoted the lipid metabolism of tumor cells." (PMID 40296917, 2025). "For instance, FASN inhibition leads to reduced levels of immunosuppressive lipids within the tumor, enhancing the recruitment and activity of effector T cells." (PMID 40376583, 2025).
tumor (continued). "Mechanistically, FASN activity in tumor cells upregulates immune checkpoint expression, particularly by promoting modification of immune checkpoint molecules, resulting in reduced antitumor immunity." (PMID 40552664, 2025). "Mechanistically, 3‐IAA binds to the AhR receptor on tumor cells and downregulates the transcription of FASN, thereby mediating phospholipid remodeling to increase ferroptosis sensitivity." (PMID 40557796, 2025). "It is worth noting that dysregulation of FASN is a hallmark of CRC, as tumor growth and survival are largely dependent on de novo lipogenesis." (PMID 40942159, 2025). "FASN catalyzes the final step of fatty acid production and is minimally expressed in normal cells but upregulated in ESCC, where it supports tumor survival and is associated with poor prognosis." (PMID 41476608, 2025). "In lipid metabolism, it promotes de novo fatty acid synthesis by activating FASN through SUMOylation, contributing to tumor vascularization." (PMID 40842995, 2025). "Knockdown of ACLY or ACC strongly reduced tumor growth, whereas knockdown of FASN1, one of the three Drosophila FASN enzymes, marginally reduced tumor growth." (PMID 40822358, 2025). "RhoU is one of the rare atypical RSGs that is only palmitoylated and not isoprenylated, and its palmytoylation is highly regulated by fatty acid synthase (FASN), which is itself commonly overexpressed in PCa and is associated with tumor progression." (PMID 41301045, 2025). "SREBP1 (Sterol Regulatory Element-Binding Protein 1) and FASN (Fatty Acid Synthase) enhance lipid biosynthesis, promoting tumor proliferation while modulating PD-L1 expression to facilitate immune evasion." (PMID 40076502, 2025). "Conversely, FASN inhibitors like orlistat markedly slow tumor growth in HMGA1-overexpressing mouse models." (PMID 41020873, 2025). "ELISA assays further validated reduced FASN protein levels (p < 0.01), consistent with cisplatin-induced metabolic reprogramming that disrupts lipid metabolism and tumor cell proliferation." (PMID 41048966, 2025). "The N44-102 sequence of PUMA is crucial for binding to FASN and promoting lipid droplet accumulation and tumor progression." (PMID 40533456, 2025). "Overexpression of FASN likely confers resistance to apoptosis; therefore, its inhibition disrupts phospholipid synthesis, suppresses tumor proliferation, and triggers programmed cell death." (PMID 40733158, 2025). "Specifically, overexpression of FASN in mouse ovarian epithelial cell lines leads to abnormal accumulation of unsaturated fatty acids, SFAs, and TG, resulting in dysfunctional tumor-infiltrating dendritic cells." (PMID 41421797, 2025). "Targeting FASN with small-molecule inhibitors has shown promise in preclinical models, leading to reduced tumor growth and enhanced sensitivity to other therapies." (PMID 40469185, 2025). "This is consistent with prior studies demonstrating its tumor-suppressive role in UCEC through the hsa-miR-497-5p/FASN axis." (PMID 39883704, 2025). "These post-translational modifications can regulate the enzymatic activity, stability, and role of FASN in tumor metabolism." (PMID 40890129, 2025). "Pharmacological inhibition of FASN reduced tumor cell viability and slowed tumor progression in vivo." (PMID 40621620, 2025). ",231, 232, 233 FASN has emerged as a promising target for OSCC treatment, and inhibition of FASN has showed the ability to attenuate tumor size and reduce proliferation capacity." (PMID 40821122, 2025). "Noteworthy in tumor cell biology, FASN orchestrates de novo fatty acid biosynthesis and underpins drug resistance in HER2-positive breast cancer." (PMID 40303293, 2025).
tumor (continued). "Targeting FASN with specific inhibitors can reverse the exhausted T cell state and synergize with anti-PD-1 immunotherapy to exert anti-tumor effects." (PMID 41514551, 2025). "Cerulenin specifically inhibits fatty acid synthase (FASN), blocking tumor lipid synthesis, downregulating Wnt/β-catenin and IGF-1 signaling, inducing apoptosis, and inhibiting metastasis." (PMID 41020873, 2025). "It selectively inhibits the enzymatic activity of FASN, leading to reduced fatty acid synthesis and accumulation of malonyl-CoA, which can induce apoptosis and inhibit tumor growth." (PMID 40469185, 2025). "In the tumour cells, increased expression of fatty acid synthase (FAS) in the anabolic pathway converts it into fatty acids for tumour growth." (PMID 41321651, 2025). "In lung adenocarcinoma, mutant KRAS activates ERK2, which subsequently induces FASN, leading to enhanced lipogenesis and tumor progression." (PMID 40552664, 2025). "has shown that AR-resistant tumor cells promote lipid synthesis by upregulating the expression of fatty acid synthase (FASN) and ATP-citrate lyase (ACL), thereby meeting the demands of rapid proliferation and membrane structure." (PMID 40008000, 2025). "As anticipated, the simultaneous overexpression of ACC1 and FASN in Huh7 cells overexpressing MARCH8 can reverse the inhibitory effect of MARCH8 overexpression on tumor formation." (PMID 40379644, 2025). "Inhibition of FASN by chemical inhibitor reduced tumour cell viability and slowed tumour progression in mice." (PMID 40621620, 2025). "Mechanistically, FASN confers radioresistance via the Akt- and NF-κB-mediated signaling pathways because the levels of proteins upstream of FASN, such as Akt and NF-κB, are increased in radioresistant tumor cells." (PMID 40765564, 2025). "The intrinsic fatty acid synthase in ovarian cancer cells leads to abnormal accumulation of lipids in tumor-infiltrating DCs, affects the anti-tumor activity of T cells, and promotes tumor progression." (PMID 40131539, 2025). "For example, fatty acid synthase (FASN) is overexpressed in TECs, promoting lipid biosynthesis that is crucial for maintaining the structural integrity of the tumor vasculature." (PMID 40784879, 2025). "In line with this, FASN inhibition was able to reduce tumour number and tumour volume in the colon of tg/tg mice." (PMID 40890536, 2025). "FASN inhibitors affect tumor lipid metabolism, suggesting their promise in combination with other agents such as ICIs." (PMID 41281744, 2025). "The impact of FASN on in vitro spheroid formation and in vivo tumor transplantation models was further evaluated through FASN knockdown." (PMID 40901481, 2025). "Cardamonin reduced the tumor growth and fatty acid synthase of the tumors, as evidenced by decreased expression of Ki-67 and FASN." (PMID 40315213, 2025). "The tumor suppressor gene speckle-type POZ protein (SPOP), which is an E3 ubiquitin ligase, regulates lipid metabolism by reducing FASN expression and fatty acid synthesis, thereby leading to tumor suppression." (PMID 39944823, 2025). "This investigational agent aims to disrupt FASN, with ongoing evaluation to assess its impact on tumor progression and immune modulation within the TME." (PMID 41163383, 2025). "FASN plays a vital role in tumor growth and survival, demonstrating significant potential for clinical applications." (PMID 40764609, 2025). "This study reveals FGFR4 as a key driver of lipid metabolism in CRC and demonstrates that isoliquiritigenin (ISL) effectively inhibits tumor progression by targeting the FGFR4/FASN pathway." (PMID 41210688, 2025). "Previous studies have demonstrated its ability to induce apoptosis, inhibit tumor growth, and suppress metastasis, with evidence pointing to the inhibition of fatty acid synthase as a central mechanism." (PMID 41194875, 2025).
tumor (continued). "Increased activity of FASN leads to increased FAS in tumor tissues, and high concentration of fatty acids in TME leads to accumulation of fatty acids in DCs, which affects their function." (PMID 40696413, 2025). "Despite the potent anti-tumor properties of certain FASN inhibitors, clinical evaluation has encountered obstacles related to drug metabolism, such as problems with orlistat." (PMID 40821122, 2025). "In recent years, studies have shown that fatty acid synthase is overexpressed in tumors, indicating the role of fatty acids in tumor development." (PMID 40696413, 2025). "The most pronounced inhibition was reached using FASN inhibitor, orlistat, that however is a drug with off-target effects upon eight proteins with a proven role in tumor biology." (PMID 40229247, 2025). "With the increasing focus on tumor microenvironment research in recent years, FASN has been found to play a significant role in tumor growth, proliferation, and immune evasion." (PMID 40936898, 2025). "In a mouse model of ovarian cancer, up-regulation of FASN expression in tumor cells resulted in excessive lipid accumulation, which inhibited the activation of T cells infiltrating the tumor by DCs." (PMID 41306968, 2025). "Preclinical studies have shown that blocking CD36, especially in combination with FASN inhibitors and anti-PD-1 therapy, produces synergistic anti-tumor effects, suggesting a promising combinatorial treatment strategy." (PMID 41476608, 2025). "By promoting lipid synthesis, FASN supports membrane biogenesis, energy storage, and the production of lipid signaling molecules that facilitate tumor growth and metastasis." (PMID 40469185, 2025). "More importantly, the combined metabolic-targeting strategy demonstrates potential clinical value: the co-treatment of miR-532-5p and the FASN inhibitor Orlistat significantly suppressed tumor growth and LNM in vivo." (PMID 41472748, 2025). "As a central regulator of lipid metabolism, FASN is essential for the proliferation and survival of lipid phenotype tumors, reconnecting tumor cells for greater metabolic flexibility to meet their high energy demands." (PMID 39963106, 2025). "In the present study, in vitro and in vivo experiments were performed to investigate the roles and molecular mechanisms of FASN in lipid metabolism reprogramming, tumor progression, and the immune response in CRC." (PMID 40148316, 2025). "FASN, a key enzyme in fatty acid biosynthesis, is overexpressed in TNBC cells and is strongly associated with tumor aggressiveness and metastatic potential." (PMID 40510158, 2025). "We also focus on discussing specific enzyme-targeted anti-tumor inhibitors in the FA metabolic pathway, with a particular emphasis on targeting FASN and SCD, which have gained broad attention." (PMID 41421797, 2025). "Tumor-intrinsic fatty acid synthase (FASN) functions as a metabolic checkpoint that constrains T-cell immunity and represents a tractable target to improve T-cell-based therapies." (PMID 41236698, 2025). "Markers such as GLUT-1, HIF-1α, FASN, LAT-1, and CA9 have been associated with tumor aggressiveness, metastasis, and poor prognosis, particularly in PanNENs." (PMID 41458541, 2025). "Following drug administration, key enzymes involved in fatty acid synthesis, including ACC, FASN, Lipin, and ATP-citrate lyase, were all inhibited, significantly disrupting the lipid synthesis pathway and inducing apoptosis in tumor cells." (PMID 40137165, 2025). "In summary, the LINC01410/miR-532-5p/FASN metabolic axis drives lymphangiogenesis and cervical cancer metastasis within the tumor microenvironment by regulating LD dynamics and fatty acid metabolic reprogramming." (PMID 41472748, 2025). "Overexpression of FASN and ACC is associated with increased tumor aggressiveness, poor prognosis, and treatment resistance." (PMID 40391753, 2025).
tumor (continued). "For instance, FASN is significantly upregulated in gastric cancer and colorectal cancer, contributing to tumor aggressiveness and poor prognosis." (PMID 40391753, 2025). "Administration of PC (18:0|18:1) abolished the influence of FASN knockdown on the number of NK cells in the tumor tissue." (PMID 40148316, 2025). "The key enzyme fatty acid synthase (FASN), which is involved in the de novo synthesis of fatty acids, is overexpressed in tumour tissues." (PMID 40414892, 2025). "For instance, the MPS1 subtype, characterized by upregulated lipid metabolism, can be targeted with FASN inhibitors to block fatty acid synthesis, reducing tumor cell energy supply and membrane lipid production, thereby inhibiting tumor growth." (PMID 40510158, 2025). "The expression of FASN is significantly elevated in a wide range of tumor cells, supporting tumor cells'lipid requirements and promoting lipid accumulation, which results in immune escape." (PMID 40696413, 2025). "Certain important enzymes involved in fatty acid synthesis, including ATP citrate lyase (ACLY), acetyl-CoA carboxylase (ACC), and fatty acid synthase (FASN), are upregulated in tumors and linked to aggressive tumor behavior and unfavorable prognosis." (PMID 40492126, 2025). "Regulators of the lipid metabolism pathway, including ATP carboxylase cleavage enzyme (ACLY), acetyl‐CoA synthetase (ACSS), and fatty acid synthase (FASN), play important biological roles in tumor metabolic reprogramming." (PMID 41346571, 2025). "Instead, it facilitates tumor progression and lipid accumulation through mechanisms involving the key metabolic regulator, fatty acid synthase (FASN)." (PMID 40533456, 2025). "As the rate-limiting enzyme in de novo lipogenesis, FASN overexpression supplies abundant lipids to support rapid tumor growth, identifying FAM as a critical downstream effector of NiNPs." (PMID 41226659, 2025). "As for CCA, the role of FASN is still controversial since enhanced FA uptake also has a great impact on tumor progression." (PMID 40507339, 2025). "COP1 ubiquitinates FASN to prevent excessive lipid accumulation, while mutations in SPOP impair FASN degradation, promoting tumor growth." (PMID 40370434, 2025). "OM and CM exhibited similarities in tumor morphology, expression of adipophilin, FASN, and GLUT1, and Ki‐67 proliferation index." (PMID 40867038, 2025). "Consistently overexpressed; enhances tumour growth, migration, and invasion by stabilizing FASN and supporting cholesterol synthesis." (PMID 41149452, 2025). "Lipid droplet and cholesterol ester accumulation are hallmarks of ccRCC, and tumor cells express critical enzymes driving lipogenesis, including fatty acid synthase (FASN), unsaturated fatty acid synthase (SCD), and long-chain lipoacyl-CoA synthase (ACSL)." (PMID 41555916, 2025). "This unexpected oncogenic function of PUMA identifies it as a promising therapeutic target and suggests a synergistic effect when combined with FASN inhibitors to inhibit tumor growth in ccRCC." (PMID 40533456, 2025). "Gene knockdown and rescue experiments demonstrated that PITPNC1 can regulate the expression of CD155 on the surface of tumor cells through FASN." (PMID 38291470, 2024). "Previous studies have found that inhibiting FASN activity resulted in a robust decline in tumor growth and dramatically induced apoptosis in DLBCL." (PMID 38195819, 2024). "When methylation across the FASN gene body was summarized as the mean beta value across all 56 probes for each sample, tumor samples were significantly hypomethylated compared with matched benign tissue in a matched analysis (P < 0.0001)." (PMID 38112617, 2024). "Luteolin, a potent FASN inhibitor with anti-tumor activity in CRC, likely operates by interfering with various signaling pathways, including the IGF-1 and Wnt-beta-catenin pathways." (PMID 39119332, 2024).